DNM1 (dynamin 1)
Diseases named in the same sentence as DNM1 in open-access papers (continued):
Sharing a sentence is not in itself a finding about the gene and the disease.
amyloidosis (1 paper, 2021). A disorder characterized by the localized or diffuse accumulation of amyloid protein in various anatomic sites. "The MMSE‐correlated DEPs were mainly involved in amyloidosis (DNM1, UBR1, OPTN, FERMT2), CNS disorder (WIPF1) and energy metabolism (COA6, COX7C, PDPR) processes." (PMID 34528736, 2021). "Specifically, the proteins involved in amyloidosis, including optineurin (OPTN), ras‐related protein Rab‐21 (Rab21), dynamin 1 (DNM1), peroxisomal bifunctional enzyme (EHHADH), fermitin family homolog 2 (FERMT2), E3 ubiquitin‐protein ligase UBR1 were increased in T2DM‐MCI compared with T2DM‐nMCI." (PMID 34528736, 2021).
Atrophy (1 paper, 2022). Any weakening or degeneration, especially through lack of use. "More generally, genetic aberrations of many of the differentially methylated genes in our study, i.e., TRIO, NRXN2, SYN2, CACNA1E, DNM1 and RAB11B, have been associated with movement disorders, cognitive and visual impairments and brain abnormalities (e.g., atrophy, white matter apoplasia)." (PMID 35094644, 2022).
Charcot-Marie-Tooth neuropathy (1 paper, 2019). "More interestingly, mutations in dynamin 2 can also cause a dominant form of Charcot-Marie-Tooth neuropathy, and recently it was reported that mutations in another dynamin family member, dynamin 1, cause encephalopathy." (PMID 31680794, 2019).
Chronic pain (1 paper, 2025). Persistent pain, usually defined as pain that has lasted longer than 3 to 6 months. "Among the 42 new chronic pain loci that harbor protein-coding variants, five genes (HECTD3 (chr1.p34.3), CCDC17 (chr1.p34.3), DNM1 (chr9.q33.1), PCDHA1 (chr5.q31.5), and WDR90 (chr16.p13.3)) showed evidence of colocalization in more than one brain tissue." (PMID 40297705, 2025).
deafness (1 paper, 2019). An inherited or acquired condition characterized by the complete loss of the ability to hear from one or both ears. "Variants with a potentially recessive effect were only found in DNM1 (family W17-4352), a gene that is associated with deafness in mouse." (PMID 30535804, 2019).
depression (1 paper, 2015). "The excitatory Dnm1 deleted mice also displayed decreased motivation, increased depression and anxiousness." (PMID 26125563, 2015).
dysautonomia (1 paper, 2025). An acute or chronic disorder, affecting the sympathetic or parasympathetic nervous system. "It is crucial to emphasize that certain symptoms cannot be fully attributed to the DNM1 variant, such as axonal sensory polyneuropathy and dysautonomia (manifesting as hyperhidrosis and nocturia in the patient)." (PMID 40717768, 2025).
gastric adenocarcinoma (1 paper, 2022). "According to reports, DNM1 promotes the growth of tumors in a number of malignancies, including gastric adenocarcinoma." (PMID 36313669, 2022).
hepatocellular carcinoma (1 paper, 2024). A malignant tumor that arises from hepatocytes. "Previous studies have found that high expression of DNM1 is an independent prognostic biomarker for poor OS in patients with hepatocellular carcinoma." (PMID 38167056, 2024).
Hyperglycemia (1 paper, 2023). An increased concentration of glucose in the blood. "Impairment of DNM1 causes insulin secretion failure and hyperglycemia in mice while inhibiting the expression of EP300 reduces adiposity in larval zebrafish." (PMID 37620670, 2023).
insomnia (1 paper, 2022). A sleep disorder characterized by difficulty in falling asleep and/or remaining asleep. "In vitro mutants in vesicular trafficking protein, dynamin-1, have impaired ability to recycle neurotransmitter at synapses, providing a more obvious potential link with insomnia." (PMID 35711912, 2022).
Leigh syndrome (1 paper, 2025). A progressive neurological disease defined by specific neuropathological features associating brainstem and basal ganglia lesions. "Pathogenic DNM1-related mitochondrial disorders with Leigh syndrome phenotype may show long-term improvement of hyperkinetic movements after GPi-DBS." (PMID 40717768, 2025).
osteoporosis (1 paper, 2023). A condition of reduced bone mass, with decreased cortical thickness and a decrease in the number and size of the trabeculae of cancellous bone (but normal chemical composition), resulting in increased fracture incidence. "While this pathway has also appeared in analyses of differentially expressed genes in post-menopausal osteoporosis, roles of specific differential genes, such as Cplx2, Cacna1b, and Dnm1, have not been investigated." (PMID 36788807, 2023).
ovarian carcinoma (1 paper, 2025). A malignant neoplasm originating from the surface ovarian epithelium. "To investigate the functional role of DNM1, we utilized an isogenic ovarian cancer model derived from the HEYA8 cell line, where highly metastatic (HM) cells exhibited increased migration and peritoneal metastasis compared to non-metastatic (NM) cells." (PMID 40205990, 2025). "In TCGA ovarian cancer samples, DNM1 expression negatively correlated with E-cadherin and positively correlated with N-cadherin." (PMID 40205990, 2025). "Here, our bioinformatic analysis of multiple TCGA datasets has identified DNM1 as a novel mediator of EMT in ovarian cancer metastasis, facilitating N-cadherin endocytic recycling independent of TGF-β." (PMID 40205990, 2025). "Moreover, we confirmed higher DNM1 expression in intermediate and mesenchymal ovarian cancer cell lines compared to epithelial lines." (PMID 40205990, 2025).
psychological distress (1 paper, 2024). "This difference remained statistically significant after log-normal GLM adjusted for age, education years, and psychological distress, interpreted as cancer patients having baseline DNM1 levels that were 32 ​% lower than non-cancer controls (RC ​= ​0.68, 95 ​% CI ​= ​0.47 to 0.98, P ​= ​0.041)." (PMID 39516074, 2024). "While some human data were collected during COVID-19 pandemic wherein social isolation and higher stress levels may have impacted DNM1 levels among non-cancer controls, our multivariable model has accounted for numerous factors including psychological distress and fatigue." (PMID 39516074, 2024).
schizophrenia (1 paper, 2016). A major psychotic disorder characterized by abnormalities in the perception or expression of reality. "Microtubule-associated proteins (MAPs) with differential abundance in schizophrenia encompassed microtubule-associated proteins 1A (MAP1A), 2 (MAP2), and tau (MAPT), and dynamin 1 (DNM1)." (PMID 26909022, 2016).
status epilepticus (1 paper, 2022). Status epilepticus is defined as a continuous seizure lasting more than 30 min, or two or more seizures without full recovery of consciousness between any of them. "Of the 20 patients, three had status epilepticus (SE); two harbored SCN1A variants and the other had a DNM1 variant." (PMID 36119689, 2022).
cancer (13 papers, 2017 to 2025). A tumor composed of atypical neoplastic, often pleomorphic cells that invade other tissues. "In conclusion, we found that downregulation of DNM1 is linked with the onset of CRCI and is consistent in both cancer patients and tumor-bearing mice receiving chemotherapy, strengthening our speculation on DNM1 role as a mediator for CRCI." (PMID 39516074, 2024). "Noncancer WT female mice treated with ADR-CYP were also included to compare DNM1 expression with the cancer-bearing mice." (PMID 39516074, 2024). "The median DNM1 levels at baseline (pg/ng of Flotillin-1) was significantly lower among cancer participants (29.7 vs 46.1, P ​= ​0.004)." (PMID 39516074, 2024). "The results showed that the expression levels of DNM1, MEIS1, and SUSD3 were associated with many cancer immune checkpoints." (PMID 38167056, 2024). "We are the first to quantify DNM1 levels within peripheral blood in human samples, and to add to the existing literature regarding the potential of EVs as biomarkers to research on cancer-related complications." (PMID 39516074, 2024). "Upregulation of clathrin light chain b has been shown to couple with dynamin-1 in cancer cells, which leads to adaptive clathrin-mediated endocytosis and increases metastasis." (PMID 37920509, 2023). "Dynamin 1 and 2 both enhance cancer cell proliferation, tumor invasion and metastasis, whereas dynamin 3 has tumor suppression role." (PMID 28402939, 2017). "Expression of dynamin 1 is upregulated in a number of cancer cells from acute myeloid leukaemia, lung and colon adenocarcinomas, perhaps reflecting a protective function against pathways of apoptosis." (PMID 28402939, 2017). "In general, dynamin 1 and 2 are overexpressed in cancerous tissue and each is related to specific cancer types." (PMID 28402939, 2017). "Others have emphasized pathways related to synaptic vesicles and key neurotransmitters (i.e., dynamin-1) being influenced by cancer and cancer treatment, which may impact the onset and severity of CRCI." (PMID 41403898, 2025). "However, in addition to neurological diseases, more and more studies have shown that DNM1 plays a role in the development of many cancers." (PMID 38167056, 2024). "Bioinformatics analyses have also identified DNM1 as a marker of invasion in this type of cancer." (PMID 36313669, 2022). "While this evidence comes from cancer cell lines, it demonstrates that DNM1 may be directly involved in suppressing pro-apoptotic signaling." (PMID 33372033, 2021). "Altogether, dynamin 1- targeted anti-cancer therapeutics may potentially to induce cancer cell apoptosis." (PMID 28402939, 2017). "Aberrant trafficking of nascent clathrin-coated vesicles and alteration of cell signalling and enhancement of cell proliferation; dynamin 1 is acutely activated by an Akt/GSK3β signalling cascade to increase the rate of CCP initiation in the H1299 cancer cells." (PMID 28402939, 2017). "In addition, given that there are reports suggesting DNM1 may enhance cancer cell growth and tumor invasion, further studies are required." (PMID 39516074, 2024). "Dynamin-1 (DNM1) and dynamin-2 (DNM2) are both cancer-promoting GTPases, yet they behave differently here." (PMID 40705199, 2025). "The results showed that DNM1, MEIS1, and SUSD3 were differentially expressed between various cancers and normal tissues." (PMID 38167056, 2024). "Activated DNM1 selectively regulates tumor necrosis factor-related apoptosis-inducing ligand (TRAIL-R2) -mediated endocytosis, allowing cancer cells to escape death." (PMID 38167056, 2024).
cancer (continued). "The results of the pan-cancer analysis showed that MEIS1 and DNM1 were significantly highly expressed in AML; MEIS1 and SUSD3 are potential risk factors for the prognosis of AML, and DNM1 is a potential protective factor." (PMID 38167056, 2024). "To study the relationship between the expression levels of DNM1, MEIS1, and SUSD3 and the prognosis of 33 kinds of cancer, we carried out a survival correlation analysis." (PMID 38167056, 2024). "DNM1 levels were 32 ​% lower (P ​= ​0.041) among cancer participants compared to non-cancer prior to treatment." (PMID 39516074, 2024). "We hypothesize that DNM1 expression is significantly downregulated among AYA cancer patients suffering from CRCI and within the hippocampus of cancer-bearing, chemotherapy-treated mice." (PMID 39516074, 2024). "Our human study was congruent with our previous study, with 46 ​% lower DNM1 expressions among cancer patients with CRCI compared to those without CRCI following exposure to neurotoxic chemotherapy." (PMID 39516074, 2024). "In particular, dynamin-1, typically neuron-specific, has been shown to be activated in nonneuronal cells via cancer-relevant signaling pathways, establishing a feedback loop between CME and signaling to enhance cancer cell survival, migration, and proliferation." (PMID 39092762, 2024). "DNM1 levels were 50 ​% lower among PCD compared to non-PCD cancer patients after exposure to neurotoxic treatment, a difference that is statistically significant (RC ​= ​0.50, 95 ​% CI ​= ​0.31 to 0.79, P ​= ​0.003), but not among controls (RC ​= ​0.78, 95 ​% CI ​= ​0.49 to 1.24, P ​= ​0.291)." (PMID 39516074, 2024). "Nevertheless, this paper establishes the potential role of DNM1 in CRCI pathogenesis and we recommend that future studies investigate the impact of different cancer types and treatment regimens on DNM1 levels and CRCI in a more appropriate homogeneous cohort of cancer patients." (PMID 39516074, 2024). "Likewise, in cancer cells and xenotransplant tumors, Drpitor1a slows cancer cell proliferation, induces apoptosis, and shrinks tumors without interfering with related GTPases such as DNM1, suggesting its high specificity as a Drp1 inhibitor." (PMID 36819102, 2023). "The Spearman correlation coefficient between changes in DNM1 and FACT-Cog total scores was statistically significant among cancer participants (rho ​= ​0.28, P ​= ​0.04), but not among non-cancer controls (rho ​= ​0.23, P ​= ​0.10)." (PMID 39516074, 2024). "By adjusting for confounders with GEE, cancer patients without PCD, on average, were found with higher DNM1 levels post-baseline compared to non-cancer counterparts (RC ​= ​2.04, 95 ​% CI ​= ​1.51 to 2.77, P ​< ​0.001)." (PMID 39516074, 2024). "Marginal analyses revealed a statistically significant decline in DNM1 levels attributable to PCD among cancer patients (Δ ​= ​−20.6, 95 ​% CI ​= ​−36.8 to −4.3, P ​= ​0.013) but not among non-cancer controls (Δ ​= ​−3.2, 95 ​% CI ​= ​−14.3 to 8.0, P ​= ​0.576)." (PMID 39516074, 2024). "First, we investigated the presence of differential DNM1 expression between cancer patients with and without perceived CRCI (adjusted for confounders) in an existing prospective cohort of newly diagnosed adolescent and young adult (AYA) cancer patients." (PMID 39516074, 2024).
tumor (9 papers, 2016 to 2024). "It is thus necessary to understand how DNM1 expression changes in the brain with tumor induction and chemotherapy administration to develop a more comprehensive picture of the DNM1-CRCI theory." (PMID 39516074, 2024). "The specific inhibitor of DNM1 (Dynasore) demonstrated a very strong and dose-dependent inhibition of tumor cell invasion." (PMID 32642662, 2019). "We identified novel protein signatures including proteolipid protein 1 (PLP1) and Dynamin-1 (DNM1) and validated them in additional tumor samples." (PMID 32642662, 2019). "At 8–9 weeks post-tumor induction, mice were euthanized, and fixed brains were collected for the immunofluorescence staining and volumetric immunoreactivity quantification of DNM1." (PMID 39516074, 2024). "Based on these observations, we speculate that the DNM1 phenotype is a result of not only properties of xenografted cells alone, but also an organismal response to the tumor, shaped by the xenografted cells' properties." (PMID 27780930, 2016). "The correlation between DNM1 expression and DNA methylation in BKPyV positive tumours has not been examined, but a significant correlation between JCPyV infection increased DNMT1 expression, and DNA hypermethylation has been found in tumours." (PMID 31408949, 2019).
neurological disease (8 papers, 2010 to 2024). "There is literature suggesting that expression of DNM1 is associated with genetic polymorphism, with some rare neurological diseases found to be caused by DNM1 mutations." (PMID 39516074, 2024). "A subset of genes was differentially expressed in the frontal cortex of RTT brains, some of which are known to be associated with neurological disorders (clusterin and cytochrome c oxidase subunit 1) or are involved in synaptic vesicle cycling (dynamin 1)." (PMID 20420693, 2010). "It is intriguing that a missense mutation in a discrete splice variant of Dnm1 can lead to significant neurological disease phenotypes." (PMID 20700442, 2010). "Dynamin-1 is very well studied, but has yet to be linked to neurological disease." (PMID 20700442, 2010). "Therefore, DNM1 is often reported to play a role in nervous system diseases." (PMID 38167056, 2024).
neurodevelopmental disorder (6 papers, 2018 to 2025). A behavioral and cognitive disorder with onset during the developmental period that involves impaired or aberrant development of intellectual, motor, or social functions. "Mutations in proteins that regulate endocytosis, such as synaptophysin and dynamin 1, have also been linked to neurodevelopmental disorders involving movement abnormalities and EEG disturbance." (PMID 30107533, 2018). "Variation in this gene has previously been linked to neurodevelopmental disorders of pain sensitivity, and changes in the expression or function of dynamin-1 could influence the synaptic regulation in chronic pain as well." (PMID 40297705, 2025). "Mutations reported in DNM1 associated with neurodevelopmental disorders." (PMID 37900685, 2023).
infection (5 papers, 2015 to 2023). The state of being infected such as from the introduction of a foreign agent such as serum, vaccine, antigenic substance or organism. "In fact, single knockdown of Cdc42, double-knockdown of Dnm1 and Dnm2 (Dnm1/2) and triple-knockdown (Dnm1/2/Cdc42) significantly blocks infection, suggesting that internalisation of the infectious seed is critical in establishing prion infection." (PMID 38102121, 2023). "At the gene level, expression of RAB8B, ACSL1 and Dynamin-1 was minimum in case of uninfected macrophages, intermediate in case of H37Ra infection and highest in the case of H37Rv infection." (PMID 28257432, 2017). "The strong downregulation of dynamin-1 at 12 hpi is therefore likely to impede viral entry and the infection process using the same mechanism as Cherax quadricarinatus which displayed reduced WSSV entry and transcription following dynamin enzymatic inhibition and RNAi knockdown." (PMID 36636327, 2022). "Taken together with the effect of clathrin heavy chain, dynamin-1, or Eps15 siRNAs on HMPV infectivity, these data indicate that CME of HMPV during entry leads to productive infection of human bronchial epithelial cells." (PMID 26629703, 2015). "Thus, while Eps15, dynamin-1, dynamin-2, dynamin-3, and clathrin heavy chain siRNAs inhibited HMPV entry and diminished infection, cells that did become infected exhibited normal amounts of surface F protein." (PMID 26629703, 2015).
cardiac diseases (1 paper, 2015). "In cardiac diseases, mitochondria dynamics is also correlated to calcium homeostasis, apoptosis, vascular smooth muscle cell proliferation, and evidences showed that decreasing mitochondrial fission due to the mutation of mitochondrial fission gene Dnm1 induces cardiomyotrophy." (PMID 26497368, 2015).
DNM1 also shares sentences with these, for which no sentence is quoted: Lennox-Gastaut syndrome (5 papers); movement disorder (4); Choreoathetosis (2); early onset epileptic encephalopathy (2); memory impairment (2); Aicardi-Goutierès syndrome (1); alcohol dependence (1); amyotrophic lateral sclerosis (1); bipolar disorder (1); channelopathies (1); cognitive decline (1); developmental and epileptic encephalopathy, 31A (1); diabetic kidney disease (1); Epileptic Seizures (1); generalized dystonia (1); glomerular diseases (1); glomerulosclerosis (1); Hyperhidrosis (1); Hypotonia (1); Hypsarrhythmia (1); infantile epileptic encephalopathy (1); liver cancer (1); lupus nephritis (1); Macrocephaly (1); membranous nephropathy (1); microcytic anemia (1); Neurodevelopmental delay (1); neuronal ceroid lipofuscinosis 4 A (1); pancreatic cancer (1); pediatric medulloblastoma (1).
A further 9 diseases each share a sentence with DNM1 in 1 paper.